SAP25 (Sin3A associated protein 25)
Description:
Involved in the transcriptional repression mediated by the mSIN3A but not the N-CoR corepressor complex.
Synonyms: FLJ00248
Tractability: No criterion of Open Targets' tractability assessment is met for any kind of drug.
Gene: Protein-coding gene on chromosome 7 (100,572,228 to 100,573,900, reverse strand). Ensembl gene ENSG00000205307.
Subcellular location: Nucleus; Cytoplasm
Subcellular location (Human Protein Atlas): Nuclear bodies
Gene Ontology:
Biological process: regulation of DNA-templated transcription
Cellular component: cytoplasm; nucleus
Genetic constraint (gnomAD): Loss-of-function variants: 22 observed, 23.68 expected, observed/expected ratio (o/e) 0.93, 90% interval 0.66 to 1.33. The synonymous counts are far from expectation, so gnomAD's model fits this gene poorly and the ratio says little. Missense variants: 350 observed, 309.17 expected, observed/expected ratio (o/e) 1.13, 90% interval 1.04 to 1.24. Synonymous variants: 173 observed, 138.14 expected, observed/expected ratio (o/e) 1.25, 90% interval 1.11 to 1.42.
Homologues: Orthologues: chimpanzee SAP25 (99% identical), macaque SAP25 (91% identical), pig SAP25 (67% identical), dog SAP25 (63% identical), mouse Sap25 (40% identical).
Diseases named in the same sentence as SAP25 in open-access papers:
SAP25 is named in the same sentence as 3 diseases in open-access papers, as found by Europe PMC text mining. Sharing a sentence is not in itself a finding about the gene and the disease. The quoted sentences say what the papers report.
leukemia (1 paper, 2017). A malignant (clonal) hematologic disorder, involving hematopoietic stem cells and characterized by the presence of primitive or atypical myeloid or lymphoid cells in the bone marrow and the blood. "SAP25 is a member of the nucleocytoplasmic shuttling proteins that are located in promyelocytic leukemia (PML) nuclear bodies." (PMID 29236770, 2017).
cancer (1 paper, 2017). A tumor composed of atypical neoplastic, often pleomorphic cells that invade other tissues. "Furthermore, it is interesting to note that upregulation of genes, such as ANKRD22, FRMD6, and KIR3DL2, and down-regulation of genes, such as TIMP3, SAP25, NAPSA, and TIMP are associated with a worse prognosis in cancer, are also associated with a worse prognosis in AdHF." (PMID 29236770, 2017).
SAP25 also shares sentences with these, for which no sentence is quoted: glioma (1 paper).